FBN1 (fibrillin 1)
Diseases named in the same sentence as FBN1 in open-access papers (continued):
Sharing a sentence is not in itself a finding about the gene and the disease.
Marfan syndrome (continued). "Indeed, after Marfan syndrome has been ruled out via the Marfan systemic scale or genetic testing for FBN1, clinicians should consider any form – possibly atypical – of collagenopathy." (PMID 41466732, 2025). "In Marfan Syndrome (MFS), increased activation of TGF-β is related in part to abnormal Fibrillin-1, which normally sequesters latent TGF-β within the ECM." (PMID 38440211, 2024). "Mutations in the fibrillin-1 gene (FBN1) are the causative factor for Marfan syndrome (MFS), a disorder of connective tissue morphology of which one of the consequences is a fragmentation of elastin fibers, which may be a reason for MFS-related aortic aneurysm." (PMID 38334666, 2024). "Furthermore, although differences in the expression levels of FBN1-related genes, such as TGFb and MMP2, were observed in our FBN1 het KO samples, these discrepancies were not identical to those observed in Marfan syndrome." (PMID 32210272, 2020). "On the other hand, if such disturbances in DNA methylation patterns in the FBN1 CpG island shore occurs at very low levels in each cell or in very few cells in tissues, it is possible that Marfan syndrome disease onset could be delayed or not occur at all." (PMID 32210272, 2020). "Although any factors causing this type of ambiguity in FBN1 CpG island shore DNA methylation patterns are still not determined, ambiguous epigenetic errors within the FBN1 CpG island shore are a new insight into elucidating haploinsufficient Marfan syndrome onset with better accuracy." (PMID 32210272, 2020). "Two case reports have associated Marfan syndrome (OMIM number 154700) with PDS/PG and suggested that FBN1 variants, while not causative for PDS, may contribute to conversion to glaucoma." (PMID 29780638, 2018). "It has been reported that antagonizing TGF-β signaling or angiotensin II signaling suppresses the development of aneurysms in Fbn1 mutant mice or Marfan syndrome patients, even though these drugs does not correct the structural problems in microfibrils caused by mutant fibrillin-125." (PMID 28252045, 2017). "In the case of Marfan syndrome, since there are ICD codes for the actual disorder, we were able to test the penetrance hypothesis by constructing a PheRS calculator for the diagnosis code rather than FBN1 variant presence or absence." (PMID 41542665, 2026). "However, truncated FBN1 proteins that escape NMD may be nonfunctional, resulting in HI, which is also known to cause severe Marfan syndrome phenotypes, including early-onset cardiac manifestations." (PMID 41256009, 2025). "Moreover, fibrillin-1 deficiency could be responsible for matrix alterations, which contribute to aortopathy associated with BAV without Marfan syndrome." (PMID 34071740, 2021). "None of these FBN1 polymorphisms is sufficiently common to rise to genome wide significance in moderately sized studies, but when several of the polymorphisms are all linked to the reduced freckling phenotype of SLC24A5, then lack of freckles can correlate with Marfan's syndrome." (PMID 23300552, 2012). "However, this is not true as fibrillin-1 is an ubiquitous protein, but the clinical consequences of extra-aortic alterations are rare in these patients, and not mentioned in European Society of Cardiology (ESC) Guidelines or a recent review on Marfan syndrome." (PMID 35360038, 2022).
ectopia lentis (77 papers, 2008 to 2025). "ADAMTSL4-related disease tends to present at a younger age and be associated with higher myopia than other forms of ectopia lentis (such as FBN1)." (PMID 41243720, 2025). "Missense mutations causing cysteine substitutions in the fibrillin-1 protein are associated with ectopia lentis, or displacement of the lens due to the loss of integrity of the lens zonules." (PMID 38983985, 2024). "We included patients <21 years old with MFS, defined by 2010 Ghent criteria and a pathogenic FBN1 variant or ectopia lentis." (PMID 38728377, 2024). "Ectopia lentis is the most common ocular manifestation in MFS due to an FBN1 mutation and is relatively specific to this disease." (PMID 38983985, 2024). "Several studies have attempted to identify genotype–phenotype correlations and to link FBN1 variant classes with risk of ectopia lentis." (PMID 37107549, 2023). "It seems that the present study’s findings are generally consistent with previous literature regarding the association between pathogenic variants involving cysteine residues in the FBN1 gene and the likelihood of ectopia lentis." (PMID 37891508, 2023). "–17,35,62 These mutants did, however, have other typical ocular manifestations associated with mammalian FBN1 mutations, that is, ectopia lentis, an elevated IOP, and a decreased visual performance." (PMID 35285860, 2022). "For ocular manifestations, in a large cohort including 1,013 probands with pathogenic FBN1 mutations, missense mutations producing or substituting cysteines were found to be related with more frequent ectopia lentis when compared with other missense mutations." (PMID 36582279, 2022). "Approximately 60% of MFS patients with FBN1 gene mutation will suffer ectopia lentis (EL) from the age of 3." (PMID 33542371, 2021). "In this cohort, 2/8 children were initially diagnosed with apparently isolated ectopia lentis but were found to carry FBN1 variants and thus benefited from regular surveillance for aortic root disease." (PMID 31848469, 2020). "Ectopia lentis is the most common ocular manifestation in MFS with FBN1 mutation (as described in the seminal paper by Maumenee in 1981) and is relatively specific to this disease when associated with other features." (PMID 32155956, 2020). "Lower expression of wild‐type FBN1 mRNA was associated with a more severe phenotype (increased risk of ectopia lentis, pectus deformities, and aortic dilatation) with variability in expression postulated from trans‐acting regulators." (PMID 31950671, 2020). "The mutation c.718C>T (p.R240C) in FBN1, identified in family 7, was first reported in 2001 (Loeys, Nuytinck, Delvaux, De, & De, 2001) in the patient who had ectopia lentis and mild cardiovascular manifestations." (PMID 30838813, 2019). "As previously shown, FBN1 expression level is a good surrogate endpoint for clinical severity, as lower FBN1 expression levels are associated with ectopia lentis and pectus excavatum." (PMID 30754709, 2019). "Currently, the diagnosis of MFS is established by the revised Ghent criteria, which includes the family history, an FBN1 mutation, aortic dilation (Z-score ≥ 2), aortic dissection, ectopia lentis and a list of systemic features." (PMID 28401471, 2017). "These genetic studies strongly linked ADAMTS17 to FBN1 and implicated it in the formation of the ciliary zonule in the eye, the fibrillin-based structure defective in ectopia lentis, and in the regulation of skeletal growth." (PMID 28176809, 2017). "Little is known about this protease or its connection to fibrillin microfibrils, whose major component, fibrillin-1, is genetically associated with ectopia lentis and alterations in height." (PMID 28176809, 2017). "FBN1 is an important component of lens zonules, and mutation of FBN1 has been found to be associated with ectopia lentis." (PMID 28177569, 2017). "ADAMTSL4, mutated in isolated ectopia lentis and ectopia lentis et pupillae, enhances fibrillin-1 assembly in cultured cells." (PMID 28176809, 2017).
ectopia lentis (continued). "ADAMTSL4 mutations cause isolated ectopia lentis (dislocation of the ocular lens) due to impaired fibrillin-1 rich suspensory ligament of the lens." (PMID 27857980, 2016). "All four patients with a mutation in cbEGF domain affecting cysteine had ectopia lentis, and their mean FBN1 mRNA level was 156 % of controls." (PMID 26684006, 2015). "An association between ectopia lentis and missense mutations in the cbEGF domain affecting cysteine residues, in the presence of normal levels of FBN1 mRNA, has been reported." (PMID 26684006, 2015). "Marfan patients with nonsense mutations of FBN1 were also reported to be with a significantly lower incidence of ectopia lentis." (PMID 24484584, 2014). "In WMS patients the ectopia lentis and dysgenesis of the lens ligament is suspected to be caused by abnormal biogenesis of fibrillin-1." (PMID 25372548, 2014). "In the absence of family history and aortic root dilatation/dissection, but presence of ectopialentis, the identification of an FBN1 variant previously associated with aortic disease is required in making the diagnosis." (PMID 24941995, 2014). "As stated, mutations in FBN1 can cause simple ectopia lentis, MFS, WMS as well as other related disorders." (PMID 23401661, 2013). "A defect in the fibrillin-1 gene (FBN1) has been demonstrated to be associated with autosomal dominant inherit ectopia lentis." (PMID 22219643, 2011). "The recent discovery of ADAMTS17 and ADAMTSL4 mutations in a WMS-like syndrome and in recessive isolated ectopia lentis respectively, further strengthen genetic associations between fibrillin-1 microfibrils and the ADAMTS superfamily." (PMID 20862248, 2010). "Eighty (44%) had ectopia lentis (including 59 patients also with pathogenic FBN1 variant)." (PMID 38728377, 2024). "A previous study showed ASPH‐mediated hydroxylation of FBN1/LTBP2 may be associated with ectopia lentis." (PMID 33217155, 2021). "Fibrillin-1 (FBN1) mutations cause connective tissue dysgenesis the main ocular manifestation being ectopia lentis (EL), which may be syndromic or non-syndromic." (PMID 31527767, 2020). "Indeed, lower FBN1 gene expression levels were found to be significantly associated with ectopia lentis." (PMID 30754709, 2019). "In particular, aortic ectasia resulted significantly influenced by FBN1 rare pathogenic variants and by FBN1, COL1A1 and COL3A1 VUS, arachnodactyly resulted influenced by FBN1 rare pathogenic and VUS rare variant; MYH11 pathogenic variants and FBN1 VUS resulted associated with ectopia lentis." (PMID 31536524, 2019). "However, there are families affected with only one of these systems, carrying FBN1 inherited variants (i.e. ascending aortic aneurysm and dissection, isolated ectopia lentis and isolated skeletal features)." (PMID 26875674, 2016). "Revised Ghent criteria for MFS diagnosis, establishes four scenarios in absence of family history for a proband: Aortic root enlargement (Z-score ≥2.0) plus ectopia lentis, or with a pathogenic FBN1 variant; or with a systemic score ≥7; or with ectopia lentis and FBN1 pathogenic variant." (PMID 26875674, 2016). "The bilateral ectopia lentis, dolichostenomelia in digits, and the cysteine substitution in FBN1, the most common type of FBN1 mutation that correlates with moderate phenotypes of presumed MFS, revealed in the proband confer an additional diagnosis of MFS to this patient." (PMID 26040324, 2015). "Moreover, no data are reported in literature regarding joint hypermobility and contractures in other fibrillinopathies (ectopia lentis, Shprintzen–Goldberg syndrome, Weill–Marchesani syndrome, familial or isolated aortic aneurysms) caused by alteration of fibrillin-1 and fibrillin-2." (PMID 27812333, 2016). "In half of the children, ectopia lentis was found, which is similar to classical MFS due to FBN1 variants in exon 24–32 (53%)." (PMID 40065510, 2025).
ectopia lentis (continued). "Given the role of FBN1 in ectopia lentis in humans and other species, FBN1 should be evaluated as a potential candidate when other horses with this condition are identified." (PMID 41136527, 2025). "Regarding the MFS phenotype, we previously demonstrated that conditional deletion of FBN1 in mice leads to ectopia lentis and other MFS-relevant ocular phenotypes, such as cataracts and axial elongation." (PMID 39768188, 2024). "The phenotype and family history of affected patients with FBN1 mutation coincided with MFS except in Family 4 and Family 6, the clinical manifestations of the two families are mainly ocular defects including ectopia lentis and high myopia >6.0D." (PMID 34957211, 2021). "On the other hand, six MFS patients with a FBN1 mutations, four of whom had familiar MFS, reached the diagnosis even in the absence of aortic compromission due to either a systemic score >7 and/or ectopia lentis." (PMID 33540834, 2021). "Recently, we showed that the level of residual FBN1 expression in MFS patients with premature termination codons (PTC) was significantly associated with a few clinical features, mainly ectopia lentis." (PMID 32443863, 2020). "The expressions of FBN1_004 and FBN1_009 isoforms were similar between controls and MFS patients, and their expression levels were associated with the presence of ectopia lentis in MFS patients." (PMID 30754709, 2019). "All the genes associated with ectopia lentis phenotypes to date, (ADAMTSL4, FBN1, LTBP2, ADAMTS10, ADAMTS17) included in the clinical exome employed, revealed several genetic variants in these genes." (PMID 29751740, 2018). "For instance, several cysteine substitutions in the FBN1 gene were correlated with ectopia lentis as the sole or predominant manifestation." (PMID 23592911, 2013). "Despite the various presentations, the Ghent diagnostic criteria of MFS rely more on the presence or absence of family history, aortic root dilation, FBN1 gene mutation, and the specific findings of ectopia lentis." (PMID 40416127, 2025). "Interestingly, FBN1 SNPs that affect EGFD residues other than cysteines that are essential for AspH catalysis have also been reported to result in ectopia lentis." (PMID 41354343, 2025). "Patients with isolated ectopia lentis (FBN1 or ADAMTSL4 gene mutation) do not have skeletal involvement." (PMID 39421111, 2024). "Even if we are not able to predict the phenotype for any given FBN1 mutations, ectopia lentis has been reported more frequently in cysteine missense mutation." (PMID 32155956, 2020). "Arginine to cysteine substitutions reported in FBN1 is related to isolated ectopia lentis." (PMID 18615205, 2008). "MFS is caused by mutations in the FBN1 (fibrillin-1) [MIM: 134797] gene and is clinically characterized by a pleiotropy of skeletal (e.g., overgrowth), cardiovascular (e.g., TAAD and mitral valve prolapse), ocular (e.g., ectopia lentis) and skin abnormalities (e.g., striae)." (PMID 34281165, 2021). "However, a subset of Fbn1 mutations in two specific regions of the Fbn1 molecule have also been identified that cause WMS, which has many opposing clinical features to MFS but ectopia lentis in common with MFS." (PMID 30060141, 2018). "Also in the absence of family history and ectopialentis, but presence of aortic root dilatation/dissection a genetic test for identification of mutation in FBN1 is sufficient to establish a MFS diagnosis." (PMID 24941995, 2014).
aortic aneurysm (47 papers, 2010 to 2025). A ruptured aneurysm located in the wall of the proximal portion of the descending aorta proceeding from the arch of the aorta. "Fibronectin is necessary for correct fibrillin-1 deposition, and it is possible that increased fibronectin in MFS and in aortic aneurysm of mgR mice reflects a compensatory response to fibrillin-1 deficiency." (PMID 40392604, 2025). "Mutations in FBN1 influence the severity of aortic disease and therapeutic responses, with aortic aneurysm being the leading cause of mortality in patients with MFS." (PMID 41040364, 2025). "Genetic knockout mice with FBN1 deficiency (Fbn1−/−) die shortly after birth due to aortic aneurysm formation and rupture, suggesting that FBN1 deposition is a prerequisite for blood vessel maturation and function during neonatal life." (PMID 38269088, 2023). "Early research in our center also showed that patients with FBN1 frameshift mutations and nonsense mutations are prone to aortic dissection, and missense mutations are prone to aortic aneurysms." (PMID 33200202, 2020). "Mutations in FBN1 lead to breakdown of microfibril architecture, which can lead to aortic aneurysms and other complications." (PMID 27376074, 2016). "Among patients with a FBN1 truncating or splicing mutation, 15 suffered from life-threatening aortic dissection, 5 had severe valvular disease, while 9 had aortic aneurysm and therefore underwent prophylactic surgery." (PMID 27611364, 2016). "Association between FBN1 mutation and familial non-syndromic aortic aneurysm has been previously reported." (PMID 20937124, 2010). "Moreover, it is involved in collagen and Fibrillin-1 (FBN1) fiber formation, where mutations in collagens or FBN1 are known to give aortic aneurysms." (PMID 40981182, 2025). "Decreased circulating asprosin in rats with hypomorphic fibrillin-1 allele caused the impairment of glucose homeostasis and the elevation of proinflammatory cytokines and contributed to the formation of inflammatory diseases such as aortic aneurysms." (PMID 36846639, 2023). "Similarly, nonsense and frameshift mutations were found to be more deleterious in a cohort of 180 patients with confirmed FBN1 mutation, as they were more frequent in patients with aortic dissection than in individuals with aortic aneurysm." (PMID 34059089, 2021). "Most patients with MFS will ultimately develop cardiovascular outcomes (aortic aneurysm, valve prolapse as well as LV dysfunction, etc.)and might further progress into aortic dissection, owing to the clinical variability in FBN1 gene mutations." (PMID 29850472, 2018). "In addition, the chronic inflammatory disease present in the aortic aneurysm of MFS is produced by the FBN-1 mutation." (PMID 29483877, 2018). "By linking a clinically relevant FBN1 mutation to aneurysm pathology, this model enables mechanistic investigation of extracellular matrix–based drivers of aneurysm progression and supports the evaluation of therapeutic strategies aimed at stabilizing the aortic wall in aortic aneurysm diseases." (PMID 41040364, 2025). "Immunofluorescent microscopy was used for determining the deposition of proteins known to play a role in aortic aneurysms in humans: fibrillin-1 (FBN1), latent transforming growth factor beta binding protein 4 (LTBP4) and fibronectin." (PMID 34607531, 2021). "These include syndromic diseases associated with aortic aneurysms, including Marfan’s and Loeys Dietz Syndromes (LDS), due to mutations in TGFβ signaling genes FBN1, TGFBR1, TGFBR2, TGFB2, and TGFB3." (PMID 30307970, 2018). "mgR/mgR mice expressing only ~20% of fibrillin-1 protein rapidly develop ascending aortic aneurysms with macrophage infiltration, intimal hyperplasia, elastic fiber fragmentation, calcified media, and proteoglycan accumulation, such as aggrecan and versican." (PMID 30037098, 2018). "If true, this would open the door to approaches aimed at increasing fibrillin-1 synthesis as possible treatments for aortic aneurysm." (PMID 28708846, 2017).